MKRN1 (makorin ring finger protein 1)
Description:
E3 ubiquitin ligase catalyzing the covalent attachment of ubiquitin moieties onto substrate proteins. Acts as a negative regulator of telomerase. Has negative and positive effects on RNA polymerase II-dependent transcription.
Synonyms: RNF61
Tractability: PROTAC: UniProt records ubiquitination sites on it; ubiquitination databases record sites on it.
Gene: Protein-coding gene on chromosome 7 (140,453,033 to 140,479,552, reverse strand). Ensembl gene ENSG00000133606.
Subcellular location (Human Protein Atlas): Cytosol; Nucleoplasm
Pathways (Reactome):
Signal Transduction: AKT phosphorylates targets in the cytosol; Regulation of PTEN stability and activity
Immune System: Antigen processing: Ubiquitination & Proteasome degradation
Gene Ontology:
Molecular function: protein binding; RNA binding; ubiquitin protein ligase activity; metal ion binding
Biological process: protein polyubiquitination; protein ubiquitination
Cellular component: cytosol
Genetic constraint (gnomAD): Loss-of-function variants: 9 observed, 51.09 expected, observed/expected ratio (o/e) 0.18, 90% interval 0.1 to 0.31. The upper end of that interval is the gene's LOEUF score, 0.31, which puts it in group 1 of 6, group 1 being the genes least tolerant of losing a copy. Missense variants: 488 observed, 600.88 expected, observed/expected ratio (o/e) 0.81, 90% interval 0.75 to 0.88. Synonymous variants: 253 observed, 224.85 expected, observed/expected ratio (o/e) 1.13, 90% interval 1.01 to 1.25.
Homologues: Orthologues: chimpanzee MKRN1 (99% identical), macaque MKRN1 (99% identical), pig MKRN1 (94% identical), mouse Mkrn1 (94% identical), rat Mkrn1 (94% identical), guinea pig MKRN1 (87% identical), rabbit MKRN1 (82% identical), tropical clawed frog mkrn1 (68% identical), zebrafish mkrn1 (63% identical), Drosophila melanogaster Mkrn1 (30% identical), Caenorhabditis elegans lep-2 (29% identical), Drosophila melanogaster CG5347 (26% identical), and 2 more. Paralogues in human: MKRN3 (51% identical), MKRN2 (39% identical).
Diseases named in the same sentence as MKRN1 in open-access papers:
MKRN1 is named in the same sentence as 51 diseases in open-access papers, as found by Europe PMC text mining. Sharing a sentence is not in itself a finding about the gene and the disease. The quoted sentences say what the papers report.
metabolic syndrome (6 papers, 2018 to 2021). A cluster of metabolic risk factors for CARDIOVASCULAR DISEASES and TYPE 2 DIABETES MELLITUS. "MKRN1 deletion in mice can significantly suppress diet-induced metabolic syndrome, whereas injection of MKRN1 shRNA into obese mice reverses nonalcoholic fatty liver disease." (PMID 34504644, 2021). "Activation of AMPK by the E3 ubiquitin ligase makorin ring finger protein 1 (MKRN1) represses diet-induced metabolic syndrome." (PMID 33204402, 2020). "The second jump (p = 0.00019) was for the 11th most T2D relevant article in week 41 which concludes with ‘implicating MKRN1 as a possible therapeutic target for metabolic syndromes, such as obesity, type II diabetes, and fat liver diseases’." (PMID 32542027, 2020). "AMPK activation under depletion of Mkrn1 in mice accelerated the consumption of nutrients, including lipids, in these tissues, facilitating more energy expenditure and preventing metabolic syndromes, such as the liver steatosis, insulin resistance, and obesity induced by HFD." (PMID 31225456, 2018). "Specific ablation of MKRN1 in the mouse liver using adenovirus prevented HFD-induced lipid accumulation in the liver and blood, implicating MKRN1 as a possible therapeutic target for metabolic syndromes, such as obesity, type II diabetes, and fat liver diseases." (PMID 31225456, 2018). "Accordingly, MKRN1-null mice show chronic AMPK activation in both liver and adipose tissue, resulting in significant suppression of diet-induced metabolic syndrome." (PMID 30143610, 2018). "Consequently, MKRN1-null mice exhibit AMPK hyperactivity in liver and adipose tissue and are protected against diet-induced metabolic syndrome, whereas lowering MKRN1 expression in obese mice reversed non-alcoholic fatty liver disease." (PMID 33513781, 2021).
cervical cancer (5 papers, 2015 to 2024). A primary or metastatic malignant neoplasm involving the cervix. "This study aimed to investigate the significance of MKRN1 in cervical cancer and explore its potential as a diagnostic marker and therapeutic target." (PMID 38480859, 2024). "The current study is the first to report the features and benefits of MKRN1 as a diagnostic marker for invasive cervical cancer/CIN." (PMID 26817873, 2016). "Taken together, these results suggest that the loss of MKRN1 inhibits cervical cancer tumorigenesis through active PTEN stabilization." (PMID 26183061, 2015). "In cervical cancer patients exhibiting high expression levels of MKRN1, the protein level of PTEN is found to be lower, which is associated with a decreased 5-year survival rate." (PMID 39048965, 2024). "In cervical cancer cells, the E3 ligase makorin ring finger protein 1 (MKRN1) ubiquitinates and degrades the PTEN protein." (PMID 39048965, 2024). "The results indicated that MKRN1 expression was up-regulated in cervical cancer tissues and correlated with advanced tumor stage, higher grade, and poor patient survival." (PMID 38480859, 2024). "The current study was conducted to determine if MKRN1 immunohistochemical (IHC) staining is a viable adjunct in diagnosing cervical cancer or its precursor lesions." (PMID 26817873, 2016). "In a study conducted by Lee et al11, overexpression of the MKRN1 protein correlated with cervical cancer in vivo." (PMID 26817873, 2016). "We anticipate that MKRN1 IHC staining will ultimately emerge as a useful adjunct to routine cervical cancer screening." (PMID 26817873, 2016). "In conclusion, comparative clinical performances of MKRN1 IHC staining and currently available cervical cancer screening tests indicate that HPV + MKRN1 is the ideal test combination, despite equivalent accuracy of cytology + HPV." (PMID 26817873, 2016). "Taken together, these data indicate that MKRN1 expression is an important prognostic factor in human cervical cancer, possibly due to its role in modulating a PTEN-dependent AKT inhibition pathway." (PMID 26183061, 2015). "In cervical cancer patients with high levels of pAKT and MKRN1 expression, PTEN protein levels are low and correlate with a low 5-year survival rate." (PMID 26183061, 2015). "The development of MKRN1-targeted interventions might hold promise for advancing personalized medicine approaches in cervical cancer treatment." (PMID 38480859, 2024). "The data showed that the deleterious effects of MKRN1 depletion on cells could be rescued by PTEN depletion alone in the xenografted tumours derived from the cervical cancer cell line." (PMID 26183061, 2015). "Interestingly, Mkrn1 functions as a positive-feedback regulator of the PI3K/AKT signals in cervical cancer progression because it is stabilized by AKT-mediated phosphorylation and it destabilizes Pten, which leads to further activation of the insulin signaling pathway." (PMID 31009498, 2019). "Our novel findings regarding the EGF/PI3K/AKT/MKRN1 axis leading to PTEN suppression, along with previous data on mutations in ERBB2, and PIK3CA, ultimately indicate that ERBB2- or PIK3CA-targeted drugs might be potential therapeutic treatments for cervical cancers." (PMID 26183061, 2015). "Results similar to those shown for ME-180 were also observed in other cell lines, including H1299, HepG2 and Hep3B cells and MEFs, indicating that EGF-driven regulation of MKRN1 and PTEN is not only restricted in cervical cancer cell lines." (PMID 26183061, 2015). "To determine the oncogenic effects of MKRN1-mediated inhibition of the PTEN tumour suppressor and activation of the PI3K/AKT pathway, we conducted a transwell migration assay using human cervical cancer cell lines (HeLa, ME-180 and CaSki)." (PMID 26183061, 2015).
colorectal cancer (5 papers, 2023 to 2025). A primary or metastatic malignant neoplasm that affects the colon or rectum. "In conclusion, we propose in Oxa-resistant colorectal cancer, elevated MKRN1 promotes AGC1 degradation via K11- and K29-linked ubiquitination, leading to proteasomal degradation, enhancing heat shock protein expression, and reducing oxidative stress, thereby conferring Oxa resistance." (PMID 40722058, 2025). "Colorectal cancer patients with higher MKRN1 levels exhibited shorter overall survival and disease-free survival rates in the cohort GSE17536." (PMID 40722058, 2025). "Data from GEPIA 2, which examines large TCGA and GTEx datasets, indicated that MKRN1 was expressed at higher levels in colorectal cancers compared to normal tissues, respectively." (PMID 40722058, 2025). "In this study, we aimed to investigate the specific mechanism and role of MKRN1 in colorectal cancer (CRC) development." (PMID 37620897, 2023). "It has been reported that MKRN1 contains a functional ring-finger structural domain of E3 ubiquitin ligase which may activate TGF-β signaling pathway to promote colorectal cancer metastasis." (PMID 40375984, 2025). "MKRN1-BRAF fusion was found in 22 head and neck carcinoma cases and 56 cases of colorectal carcinoma." (PMID 36923435, 2023).
Obesity (4 papers, 2016 to 2020). Accumulation of substantial excess body fat. "Together, these data support the hypothesis that MKRN1 deficiency potentially protects against nutrient overload-induced obesity through the tissue-specific regulation of AMPK." (PMID 30143610, 2018). "Collectively, AMPK activation alleviates obesity-induced insulin resistance and T2D in MKRN1-null mice." (PMID 30143610, 2018). "We first compared the body weights of male MKRN1-null mice to WT mice that were fed standard chow or an HFD to elucidate any potential role of MKRN1 in fat deposition and obesity." (PMID 30143610, 2018). "AMPK activation in mice lacking MKRN1 prevents NAFLD, insulin resistance and obesity associated with a high-fat diet (HFD)." (PMID 30143610, 2018). "Therefore, we postulated that AMPK activation in adipocytes would protect against obesity-induced BAT dysfunction and contribute to the anti-obesity effects on MKRN1-null mice." (PMID 30143610, 2018). "Here the inhibition of the E3 ubiquitin ligase MKRN1 was sufficient to chronically activate AMPK in the liver and adipose tissues and subsequently led to systemic effects by preventing hepatic lipid accumulation and insulin resistance and promoting anti-obesity effects on diet-induced obese mice." (PMID 30143610, 2018).
breast carcinoma (3 papers, 2014 to 2021). "Because MKRN1 and Fas-associated protein with death domain participate in necrosome formation and necroptosis regulation, downregulation of MKRN1 understandably has been shown to have a major inhibitory effect on tumor enlargement in breast cancer." (PMID 26817873, 2016). "For example, it was shown that MKRN1 E3 ligase is involved in the ubiquitination and degradation of FADD and can influence the rate of TRAIL-dependent apoptosis in breast cancer cells." (PMID 34830347, 2021).
melanoma (3 papers, 2020 to 2025). A malignant, usually aggressive tumor composed of atypical, neoplastic melanocytes. "Several of these fusions, such as the mentioned AGK::BRAF, KIAA1549::BRAF, and MKRN1::BRAF, have been previously reported in melanoma and other solid tumors." (PMID 40737104, 2025).
non-alcoholic fatty liver disease (3 papers, 2018 to 2021). "We demonstrate also its therapeutic effect by administering shRNA targeting MKRN1 into obese mice that reverses non-alcoholic fatty liver disease." (PMID 30143610, 2018).
cervical intraepithelial neoplasia (2 papers, 2015 to 2016). "First, to determine the clinical relevance of MKRN1 expression in human cancer, we used immunohistochemistry (IHC) to compare MKRN1 expression levels in human cervical tissue from patients with cervical intraepithelial neoplasia (CIN) or invasive cervical carcinoma." (PMID 26183061, 2015).
colitis (2 papers, 2023 to 2024). Inflammation of the colon. "According to previous research, hyperoside can improve DSS-induced colitis through MKRN1-mediated PPARγ signaling and Th17/Treg balance regulation." (PMID 39519671, 2024). "IHC staining of tissue sections from patients with CRC indicated that MKRN1 expression was more prominent in CRC tissues than in patients with colitis." (PMID 37620897, 2023).
diabetes (2 papers, 2018). "In the Mkrn1 knockout mice, glucose uptake and consumption were generally up-regulated in the adipose tissues, while gluconeogenesis was down-regulated in the liver, which corroborates the diabetes-free condition in Mkrn1 knockout mice fed HFD." (PMID 31225456, 2018).
glioma (2 papers, 2025 to 2026). A benign or malignant brain and spinal cord tumor that arises from glial cells (astrocytes, oligodendrocytes, ependymal cells). "CircVPS8 enhances glioma CSC viability, proliferation, and stemness, and suppresses ferroptosis by scaffolding MKRN1, SOX15, and HNF4A." (PMID 41601687, 2026).
Hepatic steatosis (2 papers, 2018). Steatosis is a term used to denote lipid accumulation within hepatocytes. "Thus, MKRN1 deficiency protects against diet-induced hepatic steatosis in an AMPK-dependent manner." (PMID 30143610, 2018). "The reduction in FFA-induced hepatic steatosis in MKRN1-ablated HepG2 cells and the chronic AMPK activation in the livers of MKRN1-null mice led us to investigate the effect of MKRN1 deficiency on HFD-induced NAFLD." (PMID 30143610, 2018). "The therapeutic potential of MKRN1 inhibition in hyperglycemia and hepatic steatosis was revealed using adenoviral gene specifically delivered to the liver." (PMID 31225456, 2018). "The possible curative effects of MKRN1 inhibition on hepatic steatosis and hyperglycaemia were further observed using an adenoviral gene delivery system." (PMID 30143610, 2018). "Next, AMPK activity was inhibited through adenoviral delivery of small hairpin RNAs (shRNAs) targeting AMPKα2 to determine the role of hepatic AMPK activation in the prevention of hepatic steatosis in MKRN1-null mice." (PMID 30143610, 2018).
viral infection (2 papers, 2020 to 2025). "Further viral infection experiments revealed that SalA inhibited PRRSV replication by activating the MKRN1-Nrf2-NQO1 pathway." (PMID 40999490, 2025). "MKRN1 could be considered as a potential widespread anti-viral protein since it interferes with additional virus infections." (PMID 33217981, 2020). "Further, the MKRN1 protein is efficiently degraded by the host cell proteasome, which overlaps with de novo accumulation of the viral pVII protein during the late phase of virus infection." (PMID 33217981, 2020).
bladder cancer (1 paper, 2024). "Further research should focus on elucidating the role of MKRN1 in the progression of bladder cancer and its underlying molecular mechanisms." (PMID 39742262, 2024). "Interestingly, the proliferation and migration abilities were enhanced in nicotine-treated bladder cancer cell, while this effect was blocked down by loss of MKRN1." (PMID 39742262, 2024). "Clearly, MKRN1 was significantly reduced by sh-MKRN1-1 and sh-MKRN1-2 in two human bladder cancer cell lines (5637, TCCSUP)." (PMID 39742262, 2024). "Our study first reported that MKRN1 was a tumor-promoter factor in bladder cancer, and the knockdown of MKRN1 obviously suppressed the cell proliferation and migration in bladder cancer cell." (PMID 39742262, 2024). "After knocking down MKRN1, the cell proliferations of bladder cancer cells were significantly decreased." (PMID 39742262, 2024). "Suppression of MKRN1 was found to reduce the migration and proliferation of bladder cancer cell." (PMID 39742262, 2024). "Moreover, the lack of in vivo experiments limits a more comprehensive exploration of the mechanism of MKRN1 in bladder cancer." (PMID 39742262, 2024). "Subsequently, we further validated whether nicotine mediates the progression of bladder cancer through MKRN1." (PMID 39742262, 2024). "Moreover, silencing MKRN1 led to the inhibition of bladder cancer cell migration." (PMID 39742262, 2024). "However, there is no research available on the biology role of MKRN1 in bladder cancer." (PMID 39742262, 2024).
cardiac hypertrophy (1 paper, 2025). "At the molecular level, Mkrn1 knockout reduced the expression of the fibrotic markers, Fibronectin and Collagen I, and molecular biomarkers of cardiac hypertrophy, ANP and BNP." (PMID 40546121, 2025).
colon carcinoma (1 paper, 2009). "s-MKRN1-Abs were frequently observed in patients with esophageal SCC (25%) and colon carcinoma (38%) but not in healthy donors." (PMID 19604354, 2009).
coronary artery disease (1 paper, 2022). "We entered FBXO7, RAD23A, and MKRN1 into the camp database and eventually identified 11 drugs that could be used to treat coronary artery disease, including doxorubicin, gabapentin, suxibuzone, prasterone, kawain, 5255229, decline, nalbuphine, MK-801, trimethoprim, and GW-8510." (PMID 35799780, 2022).
cyst (1 paper, 2019). A sac-like closed membranous structure that may be empty or contain fluid or amorphous material. "The smaller size of Mkrn1exS germline cysts suggests that Mkrn1 autonomously regulates germline cyst growth." (PMID 31009498, 2019).
esophageal cancer (1 paper, 2023). A primary or metastatic malignant neoplasm involving the esophagus. "Although the expression of SOX2 and MKRN1 in esophageal cancer is known, studies on their correlation have not been reported yet." (PMID 37930832, 2023).
esophageal SCC (1 paper, 2009). "s-MKRN1-Abs can be a candidate of diagnostic markers of esophageal SCC." (PMID 19604354, 2009). "Thus, s-MKRN1-Abs can be a candidate of diagnostic markers of esophageal SCC with low false positive rates." (PMID 19604354, 2009). "MKRN1 is a novel SEREX antigen of esophageal SCC, and s-NKRN1-Abs can be a candidate of diagnostic markers of esophageal SCC with high specificity." (PMID 19604354, 2009). "Densitometric analysis revealed that the relative expression levels of MKRN1 versus β-actin mRNA in esophageal SCC were approximately 2.5-fold higher than in the normal esophageal mucosa." (PMID 19604354, 2009). "The existence of antibodies against the MKRN1 gene product was examined with 73 sera of patients with esophageal SCC and 43 sera of healthy donors by Western blot analysis." (PMID 19604354, 2009). "It is plausible that MKRN1 is involved in differentiation and carcinogenesis of a certain type of esophageal SCC." (PMID 19604354, 2009). "The mRNA levels of MKRN1 were frequently higher in esophageal SCC tissues than in the peripheral normal esophageal mucosa." (PMID 19604354, 2009). "RT-PCR analysis showed that the expression of MKRN1 mRNA was frequently higher in esophageal SCC tissues than in the peripheral normal esophageal mucosa." (PMID 19604354, 2009). "Consequently, the sensitivity of serum markers to detect esophageal SCC was improved by using s-MKRN1-Abs in combination with conventional markers." (PMID 19604354, 2009). "MKRN1 was identified as a novel SEREX antigen of esophageal SCC." (PMID 19604354, 2009). "In the current study, we applied SEREX analysis to esophageal SCC, and identified MKRN1." (PMID 19604354, 2009). "Suppression of MKRN1 activity might be a novel strategy for esophageal SCC therapy." (PMID 19604354, 2009). "Although a total of 18 (25%) of 73 patients with esophageal SCC had s-MKRN1-Abs, none of the 43 healthy donors had a detectable level of s-MKRN1-Abs." (PMID 19604354, 2009). "The expression of MKRN1 is increased in half (5 out of 10 cases) but not all esophageal SCC tissues." (PMID 19604354, 2009).
esophageal tumors (1 paper, 2009). "Even in patients with early-stage (T1) esophageal tumors, s-MKRN1-Abs were positive for 3 (16%) of 19 patients." (PMID 19604354, 2009).